NRAS (NRAS proto-oncogene, GTPase)
Diseases named in the same sentence as NRAS in open-access papers (continued):
Sharing a sentence is not in itself a finding about the gene and the disease.
melanoma (continued). "Mutations in NRAS and BRAF genes, seen in a significant proportion of melanoma cases, lead to dysregulated signaling and persistent ERK activation, promoting cancer cell growth, melanoma development, and immune evasion." (PMID 39519202, 2024). "Moreover, loss of keratinocytic RXRα, a dimeric partner of VDR, combined with activated CDK4 or oncogenic NRAS generated UVB-induced melanomas." (PMID 38927967, 2024). "Recent research has demonstrated a significant correlation between NRAS mutations and shorter disease-free survival compared with melanoma patients without these mutations." (PMID 38534309, 2024). "Despite the association of NRAS-mutant tumors with chronic sun damaged skin, it is reported that UV signature lesions (C>T and CC>TT) are present in a similar proportion of NRAS- and BRAF-mutant melanomas." (PMID 38927967, 2024). "Analyzing the same database, we observed that the NRAS Q61R mutation was the most prevalent in melanoma patients (12.4%), but unlike the BRAFV600E mutation, it did not alter the TMB." (PMID 39061208, 2024). "We observed that the ATP-competitive inhibitor PHA-665752 and the non-ATP-competitive, clinical phase II inhibitor ARQ197 (tivantinib) elicited response in BMCs and conventional melanoma cell lines irrespective of the BRAF/NRAS mutation status." (PMID 38386085, 2024). "We next wondered whether the additive and synergistic behaviors of BRAF and NRAS mutant melanomas observed in vitro occur at clinically relevant drug concentrations in patients." (PMID 39199684, 2024). "BRAF and NRAS are two of the most common oncogenes involved in melanoma." (PMID 39336897, 2024). "Unlike BRAF mutants, melanoma harboring an NRAS mutation alters GTP hydrolysis to consequently activate the MAPK, PI3K, and RAS-like protein guanine nucleotide exchange factor (GEF) signaling pathways." (PMID 38732242, 2024). "Methylation of MEN1 is regulated by KRAS in lung adenocarcinoma, so it is possible that NRAS, the second most commonly mutated driver gene in melanoma, may similarly be responsible for the increased MEN1 promoter methylation observed in melanoma." (PMID 39336822, 2024). "On the other hand, reovirus predominantly replicated in NRAS- and BRAF-mutated melanoma cells." (PMID 39772250, 2024). "Using Roadmap data from primary melanocytes, and BRAF and NRAS mutant melanocytes, the authors noted that as melanocytes progressed towards melanoma, BRAF mutants exhibited a global decrease in the number of bivalent domains, while NRAS mutants had an increase." (PMID 38385532, 2024). "Furthermore, in vivo studies using a combination of ROCK inhibitors (GSK269962A or fasudil) with MEK or ERK inhibitors suppressed NRAS mutant melanoma growth." (PMID 39273383, 2024). "Additionally, molecular profiling plays a key role in the diagnosis and staging of melanoma, as AM cells often exhibit distinct genetic mutations; for instance, in the BRAF, NRAS, and c-KIT genes." (PMID 39519055, 2024). "Conversely, the oncogenic mutations, such as BRAF and NRAS, frequently found in other melanomas are generally absent in DMs." (PMID 38247727, 2024). "Melanoma arising from a congenital nevus is characterized by activating mutations in the neuroblastoma RAS viral oncogene homolog (NRAS) gene, often involving the loss of the normal allele and amplification of the mutant NRAS." (PMID 39202970, 2024). "A correlation has been shown between NRAS mutation and loss of CDKN2A expression through promoter hypermethylation, potentially explaining the loss of p16INK4A in BRAF/MEK inhibitor-resistant melanoma with NRAS mutations." (PMID 39501277, 2024).
melanoma (continued). "Thus, development of inhibitors of NRAS would address a critical unmet need to treating primary tumors harboring NRAS mutations as well as BRAF-mutant melanomas, which frequently develop resistance to clinically approved BRAF inhibitors through NRAS mutation." (PMID 39379700, 2024). "This study uncovers an essential interplay between the eIF4F translation initiation complex, which contributes to melanoma resistance, and the extracellular signal-regulated kinase (ERK) signaling pathway, the primary therapeutic target in melanomas with BRAF and NRAS mutations." (PMID 39436655, 2024). "Key genetic drivers central to melanoma development, such as mutations in the BRAF, NRAS, and c-KIT genes, are discussed alongside the latest WHO classification, which categorizes melanomas based on cumulative sun damage (CSD), which correlates with specific molecular alterations." (PMID 38474231, 2024). "NRAS mutation in melanoma seems to be a prognostic marker of worse prognosis and more aggressive disease, with several studies indicating that OS for patients with NRAS-mutant melanoma is significantly lower compared to those with BRAF-mutant or NRAS/BRAF-wildtype tumor status." (PMID 39410017, 2024). "In addition, double targeting effects on CDK4/6 and mutant-BRAF or MEK can regress strong and persistent melanomas with BRAF- and NRAS-mutations in preclinical studies." (PMID 38462618, 2024). "This is similar to our case because CMN gene testing was not performed, but it is certain that the intracranial malignant melanoma in our case was caused by NRAS mutations." (PMID 39650061, 2024). "This shows that the mutational context creates a different need for dosing of the two combination agents, where leveraging synergy in NRAS mutant melanoma is better achieved at intermediate doses of Cobimetinib that lower the requirement of Belvarafenib to synergize." (PMID 39199684, 2024). "While cases with BRAF TCGA driver mutations alone were consistent with previously reported data suggesting a predominance of class I mutations in BRAF mutant melanoma, only one of eleven BRAF co-mutated cases (co-occurring with either NRAS or NF1) exhibited a class I BRAF mutation." (PMID 38611025, 2024). "NRAS-mutant melanomas are typically located on the upper extremities." (PMID 38396984, 2024). "In melanomas, the MAPK pathway is activated by mutations in BRAF and NRAS genes." (PMID 39195270, 2024). "NRAS-mutant melanoma is usually accompanied by aggressive and rapid disease progression." (PMID 38067230, 2023). "However, to identify the direct binding partners of p38 in the context of NRAS-mutant melanoma cells, more sophisticated experiments such as mass spectrometry or other protein pull-down assays would be necessary." (PMID 36765834, 2023). "Therefore, p38 plays a tumor suppressive role in NRAS-mutant melanomas at least partially through the mechanism of mTOR upregulation, suppressed autophagy, and reduced actin polymerization." (PMID 36765834, 2023). "These melanoma cell lines contain different mutations in genes such as BRAF and NRAS which activate the same cell signalling pathways as that of the integrin ligation, so this could affect their responsiveness to integrin antagonists." (PMID 37627051, 2023). "A potential explanation for this finding it that as the NRAS and BRAF genes are both involved in the MPAK pathway, activating mutations of the NRAS gene in BRAF-wild type melanoma or the BRAF gene in BRAF-mutant melanoma may lead to a similar phenotype." (PMID 36836460, 2023).
melanoma (continued). "Since a number of ABL1/2 and DDR1 inhibitors are FDA-approved for treating leukemia, these data may pave the way for testing their clinical efficacy in combination with MEK for treatment-refractory NRAS-driven melanomas." (PMID 36765910, 2023). "Similarly, a high frequency of TERT promoter aberrations is also found in NRAS mutant melanomas, making TERT activity inhibition a potential therapeutic target in this population." (PMID 37239381, 2023). "However, the contribution of ABL1/2 to MEKi resistance in NRAS-mutant melanomas represents a gap in our knowledge." (PMID 36765910, 2023). "Several researchers investigated potential targeted treatments for NRAS Q61 mutant melanomas." (PMID 38003476, 2023). "There has been a suspicion that the natural history of BRAF and NRAS mutant melanoma is more aggressive than melanomas lacking these mutations." (PMID 37444637, 2023). "Interestingly, BRAF-mutated melanoma cells are generally NRAS wild type, and vice versa; thus, BRAF and NRAS mutations are considered mutually exclusive at the single cell level." (PMID 36978794, 2023). "BRAF inhibitors, including vemurafenib and dabrafenib, have demonstrated efficacy in patients with BRAF-mutated melanoma; however, no targeted therapy has been approved for patients with melanoma harboring NRAS mutations to date." (PMID 36600247, 2023). "However, using a large panel of NRAS- and BRAF-mutated cell lines as a model for MAPK-dependent melanoma, we show that MALAT1 expression is essential for melanoma colony formation, cell growth, and tumor growth." (PMID 37235843, 2023). "Coupled with the findings that BRAF inhibitors might induce ER stress in NRAS-mutant melanoma, leading to an amplification of MEK inhibitor activity, the combination of binimetinib and encorafenib might shift the balance towards better responses." (PMID 38067230, 2023). "MAPK subtype: in melanoma patients, the MAPK (mitogen-activated protein kinase) pathway, is hyperactivated causing a cascade activation of NRAS, BRAF, MEK, and ERK (MAPK), intensifying the transcription of the genes involved in cell proliferation, growth, and mutation." (PMID 36676131, 2023). "As a potential mechanism of acquired resistance, it has been reported that mutation-specific ctDNA assays allow early detection of the onset of NRAS mutation in patients treated with BRAFi, other than mutations in MAP2K1, AKT1, and PIK3CA in melanoma patients showing treatment resistance." (PMID 37627054, 2023). "Furthermore, a reduction in actin intensity in p38–high cells strongly suggests a role of mTOR in regulating actin and a remodeling in the NRAS-mutant melanoma cells." (PMID 36765834, 2023). "Using a discovery approach combining experimental models and unbiased computational analysis complemented by validation in patient biospecimens, we identified a nuclear-enriched lncRNA (AC004540.4) that is upregulated in NRAS/MAPK-dependent melanoma, and that we named T-RECS." (PMID 38077055, 2023). "These exciting data indicate that drugs targeting ABL1/2 and DDR1, many of which are FDA-approved, may be effective in conjunction with MEKi for patients with NRAS-mutant melanomas, a notoriously hard-to-treat class of patients." (PMID 36765910, 2023). "The most common oncogenic mutations in melanoma cells are BRAF and NRAS mutations." (PMID 37627116, 2023). "Following BRAF, NRAS, and NF1 comprise the next most common mutations identified in melanoma." (PMID 37900283, 2023). "Moreover, we found that these PHB ligands increase MEKi (Trametinib) sensitivity in an NRAS mutant melanoma line (MM165)." (PMID 37508519, 2023). "Notably, the effectiveness of MALAT1-ASO treatment in inhibiting the survival and proliferation of NRAS- and BRAF-mutated melanoma cells is surprising in light of MALAT1 being strongly downregulated in patient samples of melanoma." (PMID 37235843, 2023).
melanoma (continued). "Another active phase 1b trial (NCT04835805) combines pan-RAF (belvarafenib) and MEK inhibitor (cobimetinib) with and without nivolumab in patients with NRAS-mutated melanoma." (PMID 37370834, 2023). "Genomic classification based on the pattern of the most prevalent significantly mutated genes identified four distinct subtypes of melanoma, including mutant BRAF (n = 114), mutant RAS (mainly NRAS, n = 81), mutant NF1(n = 23), and Triple-WT (wild-type, n = 36)." (PMID 38082384, 2023). "BRAF and CRAF are both required to drive ERK activation in mutant NRAS-dependent melanomas; however, the role of the various RAF proteins during resistance is unknown." (PMID 36765910, 2023). "In this manuscript, we describe a potential new therapy for patients with this subtype by characterizing the mechanism by which NRAS-mutant melanoma cells resist the effects of MEKi via short-term adaptive/intrinsic resistance and long-term acquired resistance." (PMID 36765910, 2023). "BRAF mutations are more likely to be detected in SSM, while NM is associated more strongly with the ‘non-nevus’ melanoma pathway development model and NRAS mutations." (PMID 37374151, 2023). "This is an important finding, as NRAS mutations are responsible for a significant proportion of melanomas, but no well-established NRAS-targeted therapies are yet known." (PMID 38003476, 2023). "The mutations in BRAF V600, NRAS Q61, and c-KIT occur early in melanoma development." (PMID 38003476, 2023). "To gain further insights into NRAS mutant melanoma cells’ adaptation to treatment, we integrated the bulk RNA-sequencing data with previous condition-matching single-cell data from our lab by adapting and applying a Non-negative Matrix Tri-Factorization (NMTF) approach called iCell." (PMID 37420093, 2023). "We showed that p38 activation reduced the in vitro viability of NRAS-mutant melanoma cell lines." (PMID 36765834, 2023). "The oncogenic RAS genes in melanoma cells include NRAS, KRAS, and HRAS." (PMID 36901857, 2023). "Furthermore, regarding the site of origin, differences also exist in the same subgroup: in an earlier study, we concluded that NRAS and TERT promoter mutation rates were significantly higher in sinonasal than in oral mucosal melanomas of the head and neck." (PMID 35642348, 2023). "For example, it is well established that activation of the mitogen‐activated protein kinase (MAPK) pathway is critical for melanoma development, with the mutation of genes such as BRAF, NRAS and NF1 defining around three‐quarters of non‐acral cutaneous melanoma cases." (PMID 36219477, 2023). "Notably, the dormancy state is connected with cell plasticity in NRAS- and BRAF-mutated melanomas that lead to increased survival or therapy resistance." (PMID 37504268, 2023). "We discovered that p38 plays the role of a tumor suppressor in NRAS mutant melanoma." (PMID 36765834, 2023). "Another possibility is that there may be other factors, such as other non-coding RNAs or signaling pathways, that regulate NRAS expression and compensate for the loss of MALAT1 in melanoma cell lines." (PMID 37235843, 2023). "Our previous studies demonstrated that in NRAS-mutant melanoma, the antitumor activity of the MEK inhibitor binimetinib was significantly potentiated by the BRAFV600E/K inhibitor encorafenib through the induction of ER stress, leading to melanoma cell death by apoptotic mechanisms." (PMID 38067230, 2023). "Moreover, MALAT1 expression also was significantly decreased in melanoma compared to healthy skin when put in relationship to gene expression of the MAPK pathway genes NRAS, BRAF, MEK1, MEK2, ERK1, and ERK2." (PMID 37235843, 2023). "Since ABL1/2 play important roles in driving melanoma progression and are activated by ERK pathway components (BRAF, ERK) in BRAF-mutant melanomas, we examined whether their activities are elevated during MEKi resistance in NRAS-driven melanomas." (PMID 36765910, 2023).
melanoma (continued). "Mutational profile of mucosal melanomas is known to differ from their cutaneous counterparts, suggesting a different pathway in the pathogenesis: They harbor lower BRAF and TERT, and relatively higher NRAS and KIT mutation frequencies." (PMID 35642348, 2023). "This study states that BRAF/NRAS mutations within a nevus do not play a major role in the development of melanoma from nevi." (PMID 36676131, 2023). "MEK inhibitors has been used to treat advanced NRAS-mutant melanoma." (PMID 37239381, 2023). "For instance, NRAS Q61L is one of dominant drivers of melanoma." (PMID 37221195, 2023). "Phase 2 monotherapy studies in NRAS mutant melanoma and novel combination studies are ongoing." (PMID 36600247, 2023). "In addition, increased NRAS expression was also found in BRAFV600E vemurafenib-resistant melanoma cell lines." (PMID 37834284, 2023). "Specifically, in melanoma amoeboid cells, blebbing generates plasma membrane contours that recruit curvature-sensing septin proteins as scaffolds for constitutively active mutant NRAS and effectors." (PMID 37851808, 2023). "Next, the 27 migration-enhancing compounds were validated at four concentrations, 1, 5, 25, and 125 μM, in four human melanoma cell lines, SK-MEL-30 and IPC-298 which harbor NRAS mutations, and SK-MEL-3 and A-375 which harbor BRAF mutations, using the IncuCyte system." (PMID 36774779, 2023). "Arguably, rapid detection of mutated genes using IHC allows attending clinicians to rationally select targeted therapies for neoplasms known to harbor HRAS, NRAS or KRAS p.Q61R mutations including ameloblastoma, melanoma, colorectal, urothelial and thyroid cancers, among others." (PMID 37901104, 2023). "One reason may be the lower tumor‐infiltrating lymphocyte (TIL) grade for NRAS‐mutant melanoma, which lead to a more immunosuppressed microenvironment that may affect its response to immunotherapies." (PMID 37403699, 2023). "Furthermore, we showed that MALAT1-ASO treatment significantly impaired tumor growth in vivo in a xenograft NRAS-mutant melanoma mouse model." (PMID 37235843, 2023). "PI3K-Akt signalling is constitutively activated by mutant NRAS, as well as the PTEN tumour suppressor which is found to be effected by loss of function mutations in approximately 20% of BRAF-mutant melanomas, resulting in Akt activation." (PMID 37181747, 2023). "BRAF mutations are the primary drivers of melanoma in younger patients, while in older patients, neither NRAS nor BRAF was mutated in nearly half of the patients who were tested, suggesting a polygenic or lesser-known genetic driver." (PMID 36909026, 2023). "In the QW dose expansion phase, there were no responses in 17 evaluable patients with NRAS mutation-positive melanoma naïve to RAF and MEK inhibitors; 9 patients (53%) had a best response of stable disease." (PMID 37219686, 2023). "However, NRAS- and BRAF-activating mutations can coexist within the same melanoma specimen in different melanoma subclones." (PMID 36978794, 2023). "Hence, within the field of melanoma research, it remains a major objective to find effective therapy options in the treatment of patients with NRAS-mutant melanoma." (PMID 38067230, 2023). "Patients with NRAS- and NF1- mutated melanomas tend to have a worse prognosis." (PMID 37900283, 2023). "Encorafenib increased ERK phosphorylation in NRAS-mutant melanoma cells." (PMID 38067230, 2023). "NRAS- and NRAS-BRAF-co-mutated melanomas have a less favorable prognosis than BRAF-mutated ones as there are no target therapies for NRAS mutations." (PMID 37958863, 2023). "This may be related to the synergistic effects of the compound to promote apoptosis with Vem, as previously reported in NRAS mutant human melanoma lines." (PMID 37762086, 2023). "NRAS-mutant melanoma is a highly aggressive subtype with few treatment options." (PMID 36765910, 2023).